SOX2 (SRY-box transcription factor 2)
Diseases named in the same sentence as SOX2 in open-access papers (continued):
Sharing a sentence is not in itself a finding about the gene and the disease.
lung carcinoma (continued). "Lung cancer stem-like cells propagated in spheroids and immunofluorescence experiments indicated that SOX2 was remarkably overexpressed in spheroids compared with those in corresponding parental cells." (PMID 37149646, 2023). "Lung cancer stem-like cells exhibited higher SLC7A11 expression that did lung cancer cells, and the stem cell transcription factor SOX2 activated SLC7A11, thus enhancing the resistance of lung cancer stem-like cells to ferroptosis." (PMID 37433225, 2023). "Sox genes are essential in the maintenance of stem cell status, and the overexpression of Sox-2 has been found in samples of all types of lung cancer." (PMID 37089712, 2023). "In lung cancer, indeed, SOX2 activates AKT/mTOR signaling pathway, which in turn enhances the activity of the matrix-metalloproteinase-2 (MMP2)." (PMID 38096163, 2023). "RT-qPCR and immunoblotting revealed that SMO, GLI1, and SOX2 were more actively transcribed and translated in lung cancer spheroids than in parental cells." (PMID 37149646, 2023). "And in hypoxic environment, up-regulation of OCT4 and SOX2 can induce CD133 expression in lung cancer cells." (PMID 35719973, 2022). "When knocked down SFPQ with SFPQ shRNA in lung cancer MSCs, the number of colonies was reduced and the expression of stemness marker Sox2 was inhibited in mRNA and protein levels by RT-PCR and western blot analysis." (PMID 35707369, 2022). "In mechanism, the interaction between AKT and TRIB3 was necessary for the FOXO1/AKT/SOX2 activation in lung cancer." (PMID 35473511, 2022). "Meanwhile, activated TRIB3 interacted with AKT to upregulated FOXO1 and SOX2 expression, resulting in sustained tumor progression in lung cancer." (PMID 35473511, 2022). "We then observed the effect of SFPQ on the expression of stemness marker Sox2 and colony-forming ability in lung cancer-MSCs." (PMID 35707369, 2022). "Regarding the association between SOX2 and FOX1A, one recent study found a negative regulation of FOX1A by SOX‐2 in human breast and lung cancer." (PMID 35561288, 2022). "In this study, we focused on ALDH1A1, CD133, Nanog, Oct4, and Sox2, which are transcription factors required for lung cancer pluripotency." (PMID 36551502, 2022). "Sex-determining region Y-boX 2 (SOX2), another cancer biomarker is used for diagnosing various cancer types like prostate, skin, breast and lung cancer." (PMID 36560548, 2022). "We examined the effects of CFM-F, TLM, and OSM on lung cancer stem cell (SOX2), migration (MMP1), and fibrosis (TGF-β) markers, since cancer stem cells, fibrosis and migration play a certain role in drug resistance development and cancer cell proliferation." (PMID 35745729, 2022). "The stem cell factor SOX2 can inhibit ferroptosis in lung cancer stem-like cells via upregulating SLC7A11 expression." (PMID 36266731, 2022). "In Lu99 cells, dinactin significantly downregulated ALDH1A1, Nanog, Oct4, and Sox2 mRNA expression, which are transcription factors that are required to maintain pluripotency in lung cancer." (PMID 36551502, 2022). "Previous studies in lung cancer support Sox-2–mediated resistance to EGFR tyrosine kinase inhibitors." (PMID 34546978, 2021).
lung carcinoma (continued). "The embryonic stem cell transcription factors Sox2 and Nanog are crucial in maintaining stemness features of tumorspheres originated from lung cancer." (PMID 35582384, 2021). "The SOX-2 knockdown in murine lung carcinoma cells inhibited tumor growth and metastases in C57BL/6 mice in vivo." (PMID 34885925, 2021). "The role of Sox2 in regulating tumor development and maintenance of pluripotency in lung cancer has also been documented." (PMID 34063628, 2021). "In vitro, treatment of EGFR mutant lung cancer cells with erlotinib induces Sox-2 expression, with SOX2 knockdown resulting in increased erlotinib-mediated apoptosis and delayed resistance to EGFR inhibition." (PMID 34546978, 2021). "For instance, Ciclesonide, a kind of glucocorticoid, inhibits the formation of BCSCs via the GR/YAP pathway and the lung cancer stem cells via the Hedgehog/Sox2 signaling pathway." (PMID 34445421, 2021). "Overexpression of SOX2 inhibits the chemotherapy (cisplatin)-induced cell apoptosis in lung cancer cells." (PMID 34200614, 2021). "An upregulation of Sox2 has also been found in lung cancer cells cultured on 3D cultures, such as chitosan–hyaluronan matrices and spheroids." (PMID 34771484, 2021). "Increased expression of both BCAT1 and SOX2 were also observed in H661 cells which originated from lymph node metastasis of a patient with large cell carcinoma, compared to another primary lung cancer cell line H441." (PMID 34646394, 2021). "The downregulation of transcription factor SOX-2 in cancer stem cells (CSCs) was correlated with the suppression of lung cancer growth and metastasis behavior." (PMID 34885925, 2021). "The observation that ectopic SOX2 expression results in squamous lineage restriction in autochthonous mouse models of lung cancer further demonstrates the SCC-specific oncogenicity of SOX2." (PMID 33803326, 2021). "Lung cancer cells transfected with SOX2-specific siRNASOX showed a 70% reduction in tumorsphere formation." (PMID 32033067, 2020). "Our observations suggest that ciclesonide reduced SOX2 and Hedgehog signaling, which is important for tumorsphere formation in lung cancer." (PMID 32033067, 2020). "Our results demonstrate that deubiquitinase USP4 promotes lung cancer cell stemness via upregulation of Twist1, Oct4 and Sox2 expression." (PMID 32549341, 2020). "It has been recently reported that Gal-3 promotes lung cancer stemness via the EGFR/c-Myc/Sox-2 pathway, and Oct4, a stemness-related transcription factor, favors Gal-3 expression, thus establishing a positive regulatory loop in lung CSCs." (PMID 33013832, 2020). "Together, these findings identify SOX2 as a promising target for therapeutic interventions in lung cancer." (PMID 30517668, 2020). "An immunohistochemical analysis of SOX2 expression in various lung cancer types found that SCLC tissues expressed a higher level of SOX2 than NSCLC tissues." (PMID 32130794, 2020). "The SOX2 protein is involved in several cancers, including melanoma, lung cancer, breast cancer, ovarian cancer, and pancreatic cancer, and maintains CSCs in skin, bladder, and colorectal cancers." (PMID 32033067, 2020). "Expression of USP1 was significantly correlated with expression of Oct4 and Sox2 in human lung cancers, in keeping with previous reports." (PMID 32549341, 2020). "Next, we assessed if expression of HDAC11 correlated with the expression of Sox2 in the tissues of lung cancer patients." (PMID 32170113, 2020). "Altogether, the aberrant expression of SOX2 in pancreatic cancer and lung cancer impacts cellular proliferation, stemness and epithelial-mesenchymal transition of cells thus regulating the formation of cancer stem cells." (PMID 32111825, 2020). "Our results show the role of HDAC11 in regulating Sox2 expression in lung cancer cells, with a limited effect on Oct4 and Nanog expression." (PMID 32170113, 2020).
lung carcinoma (continued). "In skin squamous cell cancer, lung cancer, oesophageal cancer and medulloblastoma, SOX2 is essential for tumour occurrence and progression by regulating the expression of genes involved in the invasion, survival and proliferation of CSC." (PMID 32596945, 2020). "Fibroblast DNA shows lower expression of both OCT-4 and SOX-2 and lung cancer DNA shows the highest expression level." (PMID 32111825, 2020). "Clinical evidence of its importance in lung cancer is further exemplified by SOX2 amplification in squamous cell and small cell lung carcinomas, and its over-expression in TIC of AD19–21." (PMID 32483123, 2020). "The gene expression of SOX2 is highly expressed in NSCLC subtypes, and the inhibition of Sox2 downregulates Wnt1/2 and c-myc gene expression, induces cell apoptosis, and reduces metastatic potential in lung cancer." (PMID 33302540, 2020). "qPCR analysis showed that SOX2 mRNA levels were significantly the highest in NCI‐H446 cells compared with the other lung cancer cell lines, and of SOX2 expression was the lowest in DMS114 cells." (PMID 32130794, 2020). "SOX2 promotes abnormal proliferation of lung cancer cells and controls tumor initiation in skin squamous cell carcinoma." (PMID 32427884, 2020). "PM2.5 exposure was associated with the induction of cancer stem cell properties, marked by upregulation of mRNA levels of pluripotency-maintaining genes including SOX2 and OCT4 and subsequent increase in the risk of lung cancer." (PMID 32098209, 2020). "The individual values for CAGE, GAGE7, and SOX2 differed significantly between the lung cancer and healthy control groups (P = 0.02, 0.04, and 0.03, respectively)." (PMID 32648227, 2020). "The YB-1/SOX2 axis needs to be further investigated in lung cancer, particularly in SCC and SCLC where the development of new therapeutic strategies is most urgent." (PMID 31632972, 2019). "As a whole, these data demonstrated that a VEGF165/SOX2/SRSF2 network controls VEGFR1 pre-mRNA splicing towards sVEGFR1-i13 expression in lung cancer cells treated with anti-angiogenic therapies." (PMID 30674935, 2019). "In a study where Sox-2 expression was downregulated in the D121 lung cancer cell line, the metastatic potential was significantly suppressed." (PMID 31470802, 2019). "It was recently reported that VEGF-A controls the expression of the transcription factor SOX2 in breast and lung cancer cells." (PMID 30674935, 2019). "In the anti-Hu antibody associated SSN patient group, 19/45 (42%) had SOX2 antibodies (16 SCLC, 2 CT/PET evidence of lung cancer, 1 metastatic oesophagogastric carcinoma)." (PMID 30445363, 2019). "Among the transcription factors, SOX2 seems to play a relevant role in lung cancer stem cells; in fact, high SOX2 levels are required to sustain self-renewal and expansion of lung cancer stem cells." (PMID 30060526, 2018). "In mice, a SOX2 vaccine inhibited the growth of the TC-1 lung cancer cell line characterized by high SOX2 production." (PMID 29385680, 2018). "Through silencing and overexpression of SOX2 in lung cancer cells it was provided evidence that SOX2 expression is required for the maintenance of stemness and tumorigenic activity of human lung cancer SP cells." (PMID 30060526, 2018). "In genetically-modified mouse models of lung cancer they confirmed that SOX2 is a key oncogenic driver in the development of lung SCC." (PMID 29596469, 2018).
lung carcinoma (continued). "For instance, siRNA knockdown of Sox2 in the CSCs population in lung cancer was found to significantly decrease tumor growth and metastases in in vivo xenograft model." (PMID 29401647, 2018). "The SOX2–EGFR positive feedback loop is also present in lung cancer cells to promote cell proliferation." (PMID 30510261, 2018). "Increased TRPM7 expression was associated with enhanced SOX2, KLF4, and CD133, Hsp90α, uPA, and MMP2 expression in lung cancer cells." (PMID 30477473, 2018). "Lung cancer stem cell markers include the transcription factor SOX2, the metabolic marker aldehyde dehydrogenase isoform 1 (ALDH1), and the cell surface markers CD133, CD44, CD166, and ABCG2." (PMID 29698587, 2018). "Previous studies revealed that SOX2 protein levels are correlated with the overall survival of patients with multiple types of cancer including esophageal and lung cancer." (PMID 28288641, 2017). "In the current study, we observed that the level of active p38 MAPK is downregulated, while the level of the stemness marker SOX2 is upregulated in lung cancer tissues as compared to normal tissues." (PMID 28460458, 2017). "We and others have shown high levels of SOX2 in lung cancer, esophageal squamous cell carcinomas (ESCC) and ovarian cancer." (PMID 28288641, 2017). "Our data reveal a novel mechanism of SOX2 upregulation in lung cancers through enhancer binding by NFATc2." (PMID 28737489, 2017). "We observed that the level of active p38 is downregulated, while the level of the stemness marker SOX2 is upregulated in lung cancer tissues as compared to normal tissues." (PMID 28460458, 2017). "SOX2 inhibits apoptosis via MAP4K4-Survivin signaling in lung cancer cells and promotes metastasis of breast and prostate cancer cells by promoting epithelial-to-mesenchymal transition via the WNT/ β-catenin signal network." (PMID 28129648, 2017). "We further investigated the effects of constitutive activation or dominant negative inhibition of p38 on the expression of SOX2 and other stemness markers in these lung cancer cells." (PMID 28460458, 2017). "Studies in esophageal, hepatocellular, oral/tongue and some lung cancers have also found a correlation between elevated SOX2 and decreased survival." (PMID 28388544, 2017). "To investigate the role of p38 in the stemness properties of lung cancer cells, we compared the levels of activated and phosphorylated p38 (p-p38) and SOX2 in 3 non-small cell lung cancer cell lines, A549, H460 and H1299." (PMID 28460458, 2017). "It has been reported that the silencing of Sox2 leading to the up regulation of apoptotic marker cleaved Caspase 3 (C-caspase 3) in lung cancer." (PMID 27371094, 2016). "In this study, we investigated the plasticity of lung CSCs/CICs by using SOX2 as a lung CSCs/CICs marker and we found a novel mechanism of dedifferentiation of lung cancer cells." (PMID 27418136, 2016). "Our study suggested that HM-3 together with a gene therapy targeting Sox2 delivered by VNP20009 was an attractive treatment option for patients with lung cancer." (PMID 27371094, 2016). "SOX2 has a crucial role in maintaining the stem cell-like phenotype in cancer cells and contributes to the pathogenesis of lung cancer by controlling cell proliferation and malignant transformation." (PMID 26780934, 2016). "Previously, it was reported that EGFR-dependent SOX2 expression or β-catenin activation by galectin-3 regulates lung cancer stem cells." (PMID 27626163, 2016). "Clearly, more studies are needed to elucidate the role of SOX2 in lung cancer progression and prognosis." (PMID 26780934, 2016).
lung carcinoma (continued). "SOX2 signaling is important in maintaining the stem cell-like phenotype of cancer cells and contributes to the pathogenesis of lung cancer." (PMID 26780934, 2016). "The results suggest the combination of antiangiogenesis agent HM-3 with gene therapy targeting Sox2 delivered by salmonella as a promising strategy for the treatment of lung cancer." (PMID 27371094, 2016). "According to our knowledge, this was the first report that attenuated salmonella with a shRNA construct targeting Sox2 was co-administered with a polypeptide inhibiting angiogenesis in the treatment of lung cancer." (PMID 27371094, 2016). "In lung cancer, SOX2 gene amplification and consequent increased expression occur most frequently in squamous cell carcinoma and to a lesser extent in adenocarcinoma." (PMID 26780934, 2016). "Co-expression network construct indicated that some of the mostly connected mRNAs and TFs were previously reported to be dysregulated in lung cancer, including SOX2, FOXF1, PTK2B, XRCC2, AML-1a (RUNX1), GATA-2 and MZF1." (PMID 26159226, 2015). "In the present study, some of the mostly connected mRNAs were already reported to be correlated with lung cancer, including SOX2, FOXF1, PTK2B and VHL." (PMID 26159226, 2015). "Taken alltogether, these results indicate that suppression of EGFR signaling in mutantEGFR-addicted lung cancer cells is highly specific in triggering transcriptionalinduction of SOX2." (PMID 25686219, 2015). "There was a positive correlation between SOX2OT and SOX2 expression levels in the same lung cancer tissue samples." (PMID 26136768, 2015). "Overexpression of SOX2 has been described in lung cancer, in particular in SCC, where it is frequently amplified and promotes cancer progression." (PMID 25785245, 2015). "In this line, how anti-SOX2 antibody responses relate to SOX2 protein expression in lung cancer remains unanswered." (PMID 24940116, 2014). "The recent demonstration that ΔNp63 is amplified and overexpressed in human squamous lung cancer and along with SOX2 function as oncogenes in a squamous differentiation program highlights the importance of p63 in lung cancer." (PMID 24533135, 2014). "SOX2, a transcription factor that plays a key role in embryonic development, has recently emerged as an attractive therapeutic target in lung cancer." (PMID 24736592, 2014). "Preclinical reports have been consistent in showing that SOX2 silencing leads to significant impairment of cell growth in lung cancer models, supporting SOX2 inhibition as a promising anticancer strategy in lung malignancies." (PMID 24736592, 2014). "Nevertheless, a few Sox2 downstream gene targets have been reported in other cancer types, including PROM1 (encoding CD133) in human lung cancer cells and ITGA6 (encoding CD49f) in human mesenchymal stem cells." (PMID 25380620, 2014). "In lung cancer, the expression of Sox2 and Msi2 was 90% and 94% respectively, and more than 85% of tissues was diffusely positive for both of the markers." (PMID 23683495, 2013). "With the exception of OCT4, other markers Bmi1, CD133, CD44, Sox2, Nanog and Msi2 mRNA and protein were abundantly expressed in lung cancer." (PMID 23683495, 2013). "In lung cancer, the common stem-cell-associated markers include Bmi1, CD133, CD44, Sox2, OCT4 and so on." (PMID 23683495, 2013). "On the contrary, in the human lung cancer cell lines (H460 and H1299), a drop in SOX2 expression was observed after administration of salinomycin (p<0.05)." (PMID 24278179, 2013).